CCR9 (C-C motif chemokine receptor 9)
Diseases named in the same sentence as CCR9 in open-access papers (continued):
Sharing a sentence is not in itself a finding about the gene and the disease.
tumor (continued). "The expression of CCR9 also reduced the sensitivity of tumor cells to chemotherapy, which promoted cancer cells invasion and metastasis." (PMID 32308544, 2020). "CCR9 promoted tumor proliferation by increasing the number of HCC cells at S phase, increasing the expression of the cell cycle regulators p21 and p27and concomitantly reducing cyclin D1 levels." (PMID 31991677, 2020). "And the invasive capability of tumor cells in response to CCL25 was inhibited by CCR9 neutralization." (PMID 32308544, 2020). "Evidence suggests that blocking the CCR9/CCL25 axis can promote tumor progression and distant metastasis." (PMID 33299869, 2020). "A. muciniphila can cause IL-12 production and increase gut-tropic CD4+ T cells, which express the chemokine receptor CCR9 in tumor beds, tumor-draining lymph nodes, and mesenteric lymph nodes to exert an adjuvant effect on the anti-PD1 response." (PMID 31293523, 2019). "Oral administration of A. muciniphila with FMT of non-responder feces restored the antitumor effect of anti-PD-1 mAb through the accumulation of CCR9+ CXCR3+ CD4+ T lymphocytes in mouse tumor beds." (PMID 31718585, 2019). "In mice, we have found tumor infiltrating T cells that express CCR9 and importantly, blockade of its ligand, CCL25, in a sarcoma model, led to increased tumor growth." (PMID 30420855, 2018). "In this context, we have described the generation and characterization of mAb 91R, which inhibits CCR9+-tumor growth on in vivo subcutaneous xenografts of human ALL in immunodeficient Rag2−/− mice." (PMID 29434597, 2018). "For CCR9 expression in tumor cells, the data are still limited, but CCR9 expression correlates with the ability of the tumor to generate metastasis in the small intestine, the main site, in addition to the thymus, of CCL25 secretion." (PMID 29434597, 2018). "Blocking CCR9 signaling in vivo had a double effect: on the one hand inhibiting primary tumor growth, but on the other hand, increasing tumor metastasis." (PMID 29652830, 2018). "This antibody has therapeutic potential for the targeted elimination of CCR9+-tumor cells, used either alone or in combination with other therapies." (PMID 29434597, 2018). "CCR9 blockade using an antibody significantly reduced the tumor cell migration in response to CCL25 stimulation." (PMID 30420855, 2018). "We identified additional subpopulations marked by expression of CCR9 which potentially represent a subtype of tumor cells in the process of migrating to the small intestine where the CCR9 ligand, CCL25, is expressed." (PMID 28148223, 2017). "This review, therefore, focuses on CCR9 induction activity and summarizes what is currently known regarding its role in cancers and its potential application in tumor-targeted therapy." (PMID 26879872, 2016). "High frequencies of CD8+CCR9+ TN correlated with prolonged OS (p < 10−4), while neutralizing the CCR9/CCL25 axis in mice stimulated tumor progression." (PMID 27461275, 2016). "This suggested that the normal function of CCR9 was profoundly immunosuppressive, which was further supported when the overexpression of CCR9 on tumour cells inhibited CTL-mediated lysis and enabled immune escape." (PMID 26861383, 2016). "It has been observed that CCR9-induced tumor proliferation and migration activity is increased with the loss of PTEN in T-ALL models, suggesting that PTEN loss can inhibit tumor metastasis." (PMID 26879872, 2016). "In extended analyses, knockdown of CCR9 in patient HLA-matched tumour-infiltrating lymphocytes also increased killing in primary malignant pancreatic or melanoma cells." (PMID 26861383, 2016). "Recently, researchers have focused on CCR9 expression in selected cancers and on how CCR9 expression can be manipulated as a potential tumor biomarker in cancer diagnosis and treatment." (PMID 26879872, 2016).
tumor (continued). "This review will examine the expression of CCR9 in cancer, recent insights into the mechanisms of CCL25/CCR9 that are involved in tumor chemoresistance and metastasis, and the potential application of CCR9-based targeted therapy." (PMID 26879872, 2016). "The interaction of CCL25/CCR9 has been shown to activate many signaling pathways in cancer, especially those involved in tumor chemoresistance and metastasis." (PMID 26879872, 2016). "CCR9 also has a role in regulation of apoptosis in tumor cell lines and in cancer patients, which makes this receptor a potential chemotherapeutic target in chronic inflammatory diseases." (PMID 27795621, 2016). "Recently, researchers have found that CCL25/CCR9 plays an important role in tumorigenesis and is mainly involved in tumor chemoresistance and metastasis, which hamper the effects of conventional surgery, radiotherapy, and chemotherapy." (PMID 26879872, 2016). "As shown in Fig7C, CCR9− M579-A2 tumors grew significantly slower than the CCR9+ tumors in response to the adoptive T cell transfer, indicating that CCR9 suppresses the anti-tumor activity of the transferred T cells in vivo as well." (PMID 25691366, 2015). "In our xenografted tumor mouse model, effective control of tumor outgrowth by the adoptively transferred TILs was only possible upon stable knockdown of CCR9 on the tumor cells in contrast to the CCR9+ tumor counterpart." (PMID 25691366, 2015). "For the in vivo analysis, 5 × 105 cells each of the CCR9+ M579-A2 (shControl) and CCR9− M579-A2 (shCCR9) tumor cell lines were subcutaneously implanted in the left and the right flank, respectively, of the NSG immune-deficient mice (scheme in Fig7B)." (PMID 25691366, 2015). "Accordingly, we observed a significant increase in STAT1 and STAT2 signaling in survivin-specific T cells upon coculture with CCR9lo MCF7 cells, suggesting that anti-tumor type-1 immune response is impeded by tumor-specific CCR9 (Fig5D and E)." (PMID 25691366, 2015). "Conversely, overexpression of CCR9 inhibited tumor lysis, demonstrating that CCR9 expression enables immune escape of cancer cells (Fig4D)." (PMID 25691366, 2015). "Other than CXCR4, we and other groups have also shown the involvement of CXCR5 and CCR9 in survival and metastasis of tumor cells in different malignancies." (PMID 25296976, 2014). "From tumor immunophenotype analysis we interpreted that higher correlation of CDKN2 A and MUC5B to step 1, BIRC5 to step 2 while CCR9 to step 6 which means their up-regulation is associated with increased antigen recognition, antigen presentation and T cell activation." (PMID 40653567, 2025). "In addition, A. muciniphila promotes the infiltration of CD4+ CCR9+ CXCR3+ T cells into the tumor site, thereby supporting a strong Th1-skewed immune response—an essential component for effective tumor control." (PMID 41030253, 2025). "Mechanistically, data in mice and patients with cancer suggest that invigorated enterotropic cytotoxic T cells expressing the chemokine receptor CCR9 replenish the tumor microenvironment in a CCL25-mediated manner and control tumor growth, resulting in improved ICB efficacy." (PMID 41042869, 2025). "We then asked whether CCL25 expression by tumor cells could condition the extent of CCR9+ cell infiltration." (PMID 41042869, 2025). "Notably, NF-κB activation also upregulates CXCL12 and CCR9 expression, creating a positive feedback loop that sustains tumor-promoting inflammation and chemokine signaling." (PMID 40607416, 2025). "It is essential to determine whether the use of CCR9 antagonists, in combination with established therapies, could decrease the recruitment of Treg cells to tumor sites while increasing CD8+ T cell infiltration." (PMID 40305493, 2025). "Exposure of CCR9+ MOLT-4 cells to DMSA-MNPs@92R under AMFs resulted in enhanced tumor cell death." (PMID 41388686, 2025).
tumor (continued). "Moreover, the CCR9/CCL25 chemokine axis plays an important role in shaping TME by attracting immune cells in the tumor, leading TME toward an immunosuppressive state." (PMID 39416786, 2024). "Notably, NAT10 suppresses CD8+ T cell recruitment and cytotoxicity through the CCL25/CCR9 axis, fostering an immunosuppressive microenvironment that exacerbates tumor progression." (PMID 39648231, 2024). "Additionally, NAT10 was shown to inhibit CD8+ T cell accumulation near the tumor via the CCL25/CCR9 axis, fostering an immunosuppressive microenvironment." (PMID 39648231, 2024). "Notably, recent research indicates that tumor cells can also express CCL25, potentially promoting the infiltration of cytotoxic, CCR9-expressing tumor-infiltrating lymphocytes into the tumor microenvironment, thereby enhancing anticancer effects." (PMID 39648231, 2024). "Interestingly, CCR9-expressing T cells have been shown to contribute to anti-tumor immunity, and their recruitment into the tumor-bed (by CCL25 intratumoral delivery) improves immunotherapy efficacy." (PMID 36875124, 2023). "This function results in intestinal metastasis of tumor cells with CCR9 expression." (PMID 38049474, 2023). "A. muciniphila can produce inosine, induce the expression of TH1 regulatory genes in CD4+ T cells, and reverse PD-1 blockade by IL-12 from dendritic cells, increasing the recruitment of CCR9+ CXCR3+ CD4+ T lymphocytes to the tumor microenvironment to kill tumor cells." (PMID 37416062, 2023). "Interestingly, previous studies have shown that this chemokine is not expressed in human or murine TNBC and that intratumoral delivery of CCL25 enhances anti-tumor effects by stimulating CCR9 + CD8 + T cell tumor infiltration." (PMID 37505292, 2023). "Furthermore, since the screening of tumor cell lines identified the pancreas adenocarcinoma tumor cell line AsPC-1 as expressing CCR9 on its surface, we conducted an in vivo experiment using subcutaneous xenotransplants of these cells into NSG mice." (PMID 35967322, 2022). "CCR9 expression levels were analyzed on normal and tumor samples of the GENT2 database." (PMID 35967322, 2022). "Furthermore, since there were no data available on survival for T-ALL samples on GENT2, we decided to analyze the survival of all tumor patients with available data, depending on CCR9 expression levels." (PMID 35967322, 2022). "We found that CCL25 significantly enhanced the proliferation and migration of SACC-LM cells, and the malignant behavior of tumor cells could be inhibited by CCR9 inhibitor (Vercirnon)." (PMID 36003306, 2022). "Next, using living and dead cell experiment, we further verified whether CCL25/CCR9 promoted the growth of tumor cells through activating AKT signaling pathway." (PMID 36003306, 2022). "In addition, a humanized version of 92R mAb (Srb1) is also able to inhibit growth of CCR9+ T-ALL tumor cells in vivo, increasing survival 2.66-fold." (PMID 35967322, 2022). "Metagenomics based on stool samples from cancer patients at the time of diagnosis reveals a correlation between clinical response to immune checkpoint inhibitors and the relative abundance of A. muciniphila recruitment of CCR9 + CXCR3 + CD4 + T lymphocytes into the mouse tumor bed." (PMID 35774450, 2022). "However, CCL25 is not expressed on TNBC cells; therefore, it was proposed to intratumorally deliver CCL25 into a murine TNBC model in order to increase CCR9+CD8+ T-cell infiltration in the tumor." (PMID 35335881, 2022). "In addition to directing lymphocyte trafficking to the small intestine, CCR9 participates in tumor immunity and tumor development." (PMID 34939151, 2021). "Importantly, A. muciniphila was associated with enhanced infiltration of immune cells in tumor sites as CCR9+CXCR3+CD4+ T cells were migrated to the site of tumor, and CD4+ T cells to CD4+FoxP3+ T cells (Tregs) ratio was elevated." (PMID 33369247, 2021).
tumor (continued). "Moreover, recent studies have demonstrated that CCR9 can regulate many signaling pathways in cancers, especially pathways involved in tumor metastasis and chemotherapeutic resistance." (PMID 34863167, 2021). "CCR9 was correlated with chemo-resistance, tumor invasion and metastasis, which indicating that there might be cross-talk between CCR9 and cancer stem cells in the tumor microenvironment." (PMID 32308544, 2020). "Besides, the expression of CCR9 was positively correlated with ALDH1A1 expression in the same tumor microenvironment." (PMID 32308544, 2020). "Increasing the recruitment of CCR9+CXCR3+CD4+ T lymphocvtes into tumor beds." (PMID 32010123, 2019). "Moreover, in this tumor model, high levels of CCL25 were found in the tumor microenvironment and these levels were much higher than the levels found in the gut providing a possible explanation for the recruitment of these CCR9+ T cells to the tumor bed." (PMID 30420855, 2018). "Unfortunately, the association between CCR9 expression on circulating tumor cells and small intestine metastases has not been assessed." (PMID 30420855, 2018). "CCR9 expression has been also reported on circulating tumor cells." (PMID 30420855, 2018). "Interestingly, the authors observed that adenomas of the colon were able to form tumors in recipient mice and thus the tumor-initiating capacity was considerably inhibited by the anti-CCR9 antibody." (PMID 29652830, 2018). "Therefore, the mechanisms of CCL25/CCR9-induced tumor metastasis are complex and require further research." (PMID 26879872, 2016). "Chamorro and colleagues identified and developed a mouse anti-human CCR9 IgG2b monoclonal antibody (91R) that can recognize an epitope within the CCR9 N-terminal domain and that inhibits the growth of subcutaneous xenografts in mice with an 85 % reduction in tumor size compared with controls." (PMID 26879872, 2016). "However, flow cytometric analysis revealed no major alterations in the surface expression of HLA-A2 on the target tumor cell lines upon CCR9 knockdown." (PMID 25691366, 2015). "Interestingly, CCR9 was expressed at a significantly greater level in tumor tissue compared with normal tissue (p < 0.001)." (PMID 26168791, 2015). "CCR9 knockdown also caused increased tumor lysis by CTL, which was reverted by CCR9 overexpression." (PMID 25691366, 2015). "Moreover, inhibition of CCR9 expression on tumor cells facilitated immunotherapy of human tumors by tumor-specific T cells in vivo." (PMID 25691366, 2015). "Further, CCR9 expression was correlated with tumor stages (T) for SCC and AC tissues." (PMID 25296976, 2014). "The study also found that oral supplementation of Akkermansia muciniphila could restore the efficacy of PD-1 blockade after antibiotic treatment, an effect that depends on IL-12 and is mediated by increasing the infiltration of CCR9+CXCR3+CD4+ T lymphocytes into the tumor bed of mice." (PMID 39885985, 2024). "Therefore, CCR9 is considered as an attractive target for tumor therapy." (PMID 36810516, 2023). "Thus, the humanized version of 92R mAb (Srb1), displays therapeutic potential for CCR9+ tumor treatment and might represent one of the first therapeutic antibodies for precision medicine on T-ALL patients." (PMID 35967322, 2022). "This study shows that inhibiting CCR9 expression may promote tumor-specific T cell immunotherapy." (PMID 34490243, 2021). "The application of anti-CCR9 antibody could inhibit the migration and invasion of tumor cells." (PMID 32308544, 2020). "In addition, A. muciniphila can also increase the patient’s response to drugs by increasing the recruitment of CCR9+ CXCR3+ CD4+ T lymphocytes during the immunotherapy of tumor patients with PD-1/PD-L1 and increase the progression-free survival (PFS) of patients after treatment." (PMID 30687277, 2018). "Therefore, inhibiting CCR9 expression in vivo could significantly improve the effect of tumor-specific T cell-mediated immune therapy." (PMID 26879872, 2016).
tumor (continued). "So far, we have performed experimental validation on four of the identified candidates (GLIPR1L1, GHSR, CEACAM6, and CCR9, of which we here report on CCR9) using additional tumor cell lines and antigen-specific CTL clones and in all cases we could confirm their immune-modulatory function." (PMID 25691366, 2015). "Additionally, we evaluated whether CCR9 knockdown influences MHC-I expression on the tumor targets that could possibly explain their impact on T cell recognition and lysis." (PMID 25691366, 2015). "This intervention was sufficient to inhibit the recruitment of CCR9+ T cells in the TME and abrogate tumor growth control by apyrase." (PMID 41042869, 2025). "This review highlights chemokine-mediated mechanisms, focusing on CCR9/CCL25 and CXCL12/CXCR4 axes, which promote tumor growth, metastasis, and immune evasion via PI3K/AKT and MAPK signaling." (PMID 40607416, 2025). "In NSCLC, the CCR9/CCL25 interaction induced tumorigenesis and inhibited apoptosis of tumor cells by activating the PI3K/Akt signaling pathway." (PMID 39416786, 2024). "The interaction of CCR9 and CCL25 activates the phosphatidylinositide 3-kinase (PI3K)/Akt signaling pathway, which is involved in the proliferation and survival of tumor cells." (PMID 36810516, 2023). "On the other hand, CCR9 is the unique receptor of CCL25, a chemokine whose expression increased in our 4T1 CSF1−/− tumor cell line." (PMID 37505292, 2023). "CC chemokine receptor 9 (CCR9), an organ-specific chemokine receptor, interacts with its exclusive ligand CCL25 to promote tumor proliferation and metastasis." (PMID 36003306, 2022). "On the other hand, oral supplementation of non-responder patients with A. muciniphila upon FMT restored the anti-PDCD1 efficacy via IL12 by increasing the recruitment and infiltration of CXCR3+, CCR9+, CD4+ T cells into the mouse tumor site." (PMID 35463305, 2022). "Interestingly, the tumor cell infiltrates in the livers of MOLT4-GFP xenografts displayed a completely different pattern than the infiltrates in the livers of xenotransplants from the T-cell leukemia cell line Jurkat-GFP (selected for being CCR9-), as demonstrated by UV-stereomicroscopic imaging." (PMID 35967322, 2022). "In conclusion, targeting CCR9/CCL25 is expected to be a new approach for treating tumors, by suppressing or treating tumor patients with an autoimmune system that produces a lasting antitumor response." (PMID 34490243, 2021). "It has been demonstrated that normal gut microbiota might enhance the anti-tumor activity of ICIs by promoting the secretion of IL-12 by local dendritic cells and by changing the local repertoires of Th1 cells to express the intestinal chemokine receptors CCR9 and CXCR3." (PMID 33578709, 2021). "In the study, NP-siCD47/CCL25 remarkably increased the invasiveness of CCR9+CD8+ T cells, inhibited the expression of CD47 in tumor cells, and inhibited tumor cells metastasis and growth by T-cell-dependent immunity." (PMID 34490243, 2021). "CCR9 is notably up-regulated in HCC tissues, and this was related to the presence of several tumor nodes, high Edmondson-Steiner grade and vascular invasion." (PMID 31991677, 2020). "CCR9 interacts with its exclusive ligand CCL25 and results in trafficking of both lymphocytes and tumor cells to participate in tumor immunity and tumor development 11, 16, 17, 27-30." (PMID 32308544, 2020). "Consistently, “good” bacteria introduction was reported to significantly increase IFN-γ production in spleen and tumor-draining lymph nodes (TDLN) and induce DCs to secrete IL-12, resulting in increased recruitment of CCR9+CXCR3+CD4+ T cells into tumor beds." (PMID 33194652, 2020). "The first two strategies eliminate tumor cells by targeting the CCL25–CCR9 interaction, whereas the last directly targets the cells expressing CCR9." (PMID 29434597, 2018). "CCR9, and CCL20, which are involved in promoting metastasis by enhancing tumor cell proliferation and migration." (PMID 28928458, 2017).